E2F3 (E2F transcription factor 3)
Diseases named in the same sentence as E2F3 in open-access papers (continued):
Sharing a sentence is not in itself a finding about the gene and the disease.
myeloma (1 paper, 2023). "Utx/BrafV600E plasma cells before and after overt MM showed gradual up-regulation and down-regulation of DEGs, including representative myeloma signature genes with upregulation of Myc, Ccnd2, E2f3, and Irf4 and downregulation of Cd19 and Ikzf3." (PMID 37198323, 2023).
myocardial hypertrophy (1 paper, 2024). "E2F-1 and E2F-3 are shown to be important regulators for cell proliferation, particularly E2F-1, which has been demonstrated to improving myocardial hypertrophy." (PMID 38008859, 2024).
ovarian serous adenocarcinoma (1 paper, 2019). An adenocarcinoma that arises from the ovary and is characterized by the presence of malignant epithelial cells that, in well differentiated tumors, resemble the epithelium of the fallopian tube or, in poorly differentiated tumors, show anaplastic features and marked nuclear atypia. "In Lu's dataset and Yoshihara's dataset, E2F3 was significantly overexpressed in ovarian serous adenocarcinoma with fold changes of 1.838 (p–value = 1.27E-04) and 1.833 (p–value = 5.66E-04), respectively." (PMID 30967995, 2019).
periodontitis (1 paper, 2023). An acute or chronic inflammatory process that affects the tissues that surround and support the teeth. "In addition, we discovered TFs, E2F3, ELL and ARID3A are up-regulated in periodontitis tissues compared with the healthy control, however, there was no statistical significance, there may be shortcomings of small sample size." (PMID 37495990, 2023).
Sepsis (1 paper, 2025). Sepsis is defined as life-threatening organ dysfunction caused by a dysregulated host response to infection. "We observed that sepsis decreased the levels of FOXM1 and its downstream targets, FOXO1, E2F3, and β-catenin but upregulated p21 in lung tissue." (PMID 41253746, 2025).
Stroke (1 paper, 2012). Sudden impairment of blood flow to a part of the brain due to occlusion or rupture of an artery to the brain. "The stress response following stroke induced several replication-associated genes such as CDT1 and E2F3." (PMID 23284893, 2012).
teratocarcinoma (1 paper, 2013). A germ cell tumor characterized by the presence of an embryonal carcinoma component and a teratoma component. "They reported that human stem cells and teratocarcinoma cells show a selective reduction in the expression of E2F1, E2F2, E2F3 and p105 (encoded by NFKB1) and enhanced expression of E2F4, E2F5, E2F6 and p130 (encoded by RBL2) compared with human normal somatic IMR90 cells." (PMID 24355041, 2013).
tumor (238 papers, 2005 to 2026). "Turning to transcription factors in ACC, E2F1, and E2F3 are implicated in cell cycle regulation, with overexpression potentially driving excessive cell division and contributing to tumour growth." (PMID 38524085, 2024). "Since enhanced levels of E2F3 were associated with a higher tumor stage and grade, this gene was regarded as an oncogene in BC37." (PMID 35393513, 2022). "Research shows that E2F3 can contribute to tumor development via causing excessive cell proliferation and apoptosis." (PMID 33593338, 2021). "A past research found a prognostic value of E2f3 expression in ccRCC, which was significantly associated with tumor size, metastasis, lymph node metastasis, and tumor stage." (PMID 33062672, 2020). "Amplification and overexpression of E2F3 has been shown to be closely associated with clinical stage, pathological grading, proliferation index, and tumor aggression." (PMID 30967995, 2019). "The authors demonstrated that XIST-promoted activation of E2F3 was caused by the competitive sponge role of XIST for miR-34a-5p (a well-known tumor suppressor miRNA), which targets E2F3." (PMID 29147648, 2017). "Gene expression profiling of tumor-associated macrophages revealed that E2F3 for instance, controls gene expression which are associated with cytoskeleton rearrangements, cell migration and adhesion." (PMID 26751588, 2016). "Prior data from primary UC and other cancers has suggested E2F3 amplification is associated with higher grade and stage primary tumours." (PMID 25886454, 2015). "In Rb;p107-deficient retinae, E2f1 and E2f3 inactivation rescued tumor formation but only E2f1 rescued the retinal development phenotype." (PMID 25338120, 2014). "Notably, chromatin regulators Hells and Uhrf1 were identified to be expressed in murine RB tumors, but their expression was abrogated in E2f1 or E2f3‐deficient background in the same murine RB model with a concomitant rescue of the tumor development phenotype." (PMID 32840881, 2021). "Results from the Kaplan-Meier analysis and GEPIA showed that patients with a high level of miR-573 had a significantly reduced risk of death while those with a high level of E2F3 displayed significant correlation with the tumor stage and suffered worse prognosis." (PMID 33854603, 2021). "Loss of E2F2 and E2F3 is related to a significant delay in tumor onset." (PMID 32806777, 2020). "High E2F3 nuclear (++ and +++) expression level was associated with smaller tumor sizes, lower clinical stages, incidence of microvascular invasion, and no metastatic state; whereas tumors with high cytoplasmic E2F3 (++ and +++) were positively associated with aggressive characteristics." (PMID 28903320, 2017). "Recently, it was demonstrated that EGFR/miR-145/E2F3 pathway could offer a promising strategy for tumor prevention in high-risk individuals." (PMID 28947999, 2017). "The anti-proliferative (or tumor suppressive) effect of miR-34a is associated with its role in targeting transcription factor E2F3, however the cancers that have high expression of miR-34a were shown to have low levels of E2F3." (PMID 25669974, 2015). "As described in the results section, promoter analysis supported stronger regulation of cell cycle and of lipid metabolism in the tumor state by associating motifs of Atf3, Jun, E2f3, and Pparg with corresponding tumor genes and thus supported our previous findings." (PMID 21464922, 2011). "The data also indicated that the E2F3 protein level might be associated with tumour progression as a significant difference was observed between adenocarcinomas and metastases." (PMID 19156145, 2009). "We discovered that in the 239-tumor training set, the odds-ratios of activation of src and b-catenin pathways in our high versus low-risk group were 3.42 (95% C.I. 1.89–6.18) and 2.77 (95% C.I. 1.59–4.8) respectively, while the odds-ratio for E2F3 was 0.251 (95% C.I. 0.141 – 0.446)." (PMID 21479231, 2011).
tumor (continued). "TRIM26 depletion attenuated E2F3 induced NF-κB activation and tumor growth, whereas its restoration rescued these effects." (PMID 42088415, 2026). "Promoter methylation analysis using the UALCAN database revealed that THBS2, CTNNB1, COL4A1, and E2F3 exhibited significantly lower promoter methylation levels in STAD tumor tissues compared to normal controls." (PMID 41291892, 2025). "This contextualizes the circ_0001741/miR-194-5p/E2F3 axis within a larger network of signaling pathways that influence chemotherapy response and the tumor microenvironment (TME), particularly oxaliplatin resistance." (PMID 41372977, 2025). "Crucially, the anti-tumor effects induced by circ_0001741 knockdown were significantly reversed by co-silencing miR-194-5p or overexpressing E2F3, thus establishing a functional circ_0001741/miR-194-5p/E2F3 axis in ESCC." (PMID 41372977, 2025). "The mRNA expression analysis revealed that THBS2, CTNNB1, COL4A1, and E2F3 were significantly upregulated in tumor tissues compared to normal gastric tissues in the TCGA-STAD cohort." (PMID 41291892, 2025). "E2F3 is a transcriptional activator that is amplified or overexpressed in several tumours including those of the prostate." (PMID 39337607, 2024). "used a bitransgenic mouse model of Myc-induced T cell lymphomagenesis and analyzed tumor progression in mice deficient for E2F1, E2F2, or E2F3." (PMID 38807594, 2024). "Clinical studies have found that the higher the clinical stage and pathological grade of the tumor, the higher the positive rate of E2F3 expression." (PMID 37283793, 2023). "Cell cycle proteins were evaluated based on their altered expression patterns (WAPAL, AHCTF1, etc.), phosphorylation patterns (CCNL1 T67, SMC4 S41, etc.), and inferred TF activities (SMARCA5, E2F3, etc.)in GC tumor tissues." (PMID 36788224, 2023). "We found that GC patients with high DNA binding activities of SMARCA5 and E2F3 and high phosphorylation of CCNL1 (at T67) and SMC4 (at S41) in tumor tissues associated with poor prognoses (Log-rank test, p < 0.05)." (PMID 36788224, 2023). "Meanwhile, one study indicated that exosomes derived from dying tumor cells in PDAC after radiotherapy delivered miR-194-5p and further regulated E2F3 to enhance the survival of residual tumor repopulating cells (TRCs)." (PMID 36539807, 2022). "Meanwhile, E2F3 expression appears to provide a growth advantage to tumor cells by activating cell proliferation." (PMID 36424626, 2022). "In conclusion, these results indicated that NEAT1 exerted its tumor-promotive functions on PCa by the miRNA-766-5p/E2F3 axis." (PMID 35237319, 2022). "In the present study, we provide direct evidence that Brachyury is a direct target of E2F3 and is important for E2F3 to promote tumor proliferation and migration." (PMID 36457717, 2022). "Circ-E2F3 as a tumor promoter promoted RB proliferation, metastasis, and apoptosis by modulating the miR-204-5p/ROCK1 axis." (PMID 35865469, 2022). "For example, various mouse models unequivocally showed that E2f1 and E2f3 can both act as tumor suppressors or oncogenes, depending on tissue context." (PMID 33922435, 2021). "E2F3 is critical in regulating the transcriptional activation of various oncogenes, which control the rate of tumour and progenitor cell proliferation." (PMID 34741389, 2021). "E2F3B, an isoform of E2F3, usually acts as a canonical repressor but has also been reported as an oncogene in some tumor types." (PMID 34617871, 2021).
tumor (continued). "Here, we showed that the stiffness microenvironment activates a CD36/AKT/E2F3 mechanosignaling to modulate tumor-promoting factor FGF2 expression." (PMID 34873170, 2021). "Several tumor-related miRNAs have been found to target E2F3, including miR-128, miR-377, and miR-34a." (PMID 33618745, 2021). "It has been reported that miR-34a can regulate tumor angiogenesis by directly inhibiting angiogenic functions of endothelial cells by downregulating several key proteins including E2F3, SIRT1 and CDK4 in HNSCC." (PMID 33981611, 2021). "These mouse tumour transcriptomic responses are also in keeping with our phosphoproteomics analyses which identified E2F3 as a phosphorylation target of ATR activity." (PMID 34819497, 2021). "Our study showed that circAGAP1 inhibition suppressed ccRCC tumor progression through E2F3, further demonstrating the regulatory ability of the circAGAP1/E2F3 axis in ccRCC." (PMID 33618745, 2021). "The circ_0032822 was identified as a tumor-promoting noncoding RNA in HNSCC through the miR-141/E2F3-dependent mechanism." (PMID 33981611, 2021). "CircCDR1as promoted the migration, invasion and proliferation of PC cells in vitro and tumor growth in vivo via mediating E2F3 expression by sponging miR-432-5p." (PMID 33593338, 2021). "Taken together, we demonstrated for the first time that stiffness-induced HSC activation through E2F3, and this microenvironment promoted tumor growth and metastasis." (PMID 34873170, 2021). "To validate stiffness-E2F3 effects in vivo tumor growth, we used a tumor cell/ CM co-implantation mouse model." (PMID 34873170, 2021). "About LGG, the E2F3 expression showed a positive correlation with tumor purity and infiltrating levels of B cells, CD8+ T cells, and dendritic cells but not with macrophages and neutrophils." (PMID 33381564, 2020). "The E2F3 expression was remarkably positively related to tumor purity (r = 0.219, P = 5.81e − 06) and neutrophils (r = 0.293, P = 7.29e − 11) in GBM." (PMID 33381564, 2020). "In conclusion, our results provide new evidence showing that circ_0087378 is a novel oncogenic circRNA that exerts its tumor-promoting activities in ESCC through mediating the miR-140-3p/E2F3 axis." (PMID 33680929, 2020). "We observed that E2F3 promoter activation was suppressed in RBAT1 or HNRNPL knockdown tumor cell lines." (PMID 32669100, 2020). "Exosomes derived from dying tumor cells induced G1/S arrest and promoted DNA damage response to potentiate survival of TRCs through delivering miR-194-5p, which further modulated E2F3 expression." (PMID 32228703, 2020). "We found that RBAT1 is an important transcriptional accelerator that induces E2F3 gene expression in tumor cells." (PMID 32669100, 2020). "We next performed ChIP assays and found that HNRNPL bound to E2F3 promoter in tumor cell lines (10 ~ 20-fold changes), while there are merely 2 ~ 4-fold changes in ARPE-19 and SV-HUC-1." (PMID 32669100, 2020). "Mechanistically, we showed that RBAT1 recruits the HNRNPL protein to E2F3 promoter region, which activates E2F3 signaling to prime for tumor cell proliferation." (PMID 32669100, 2020). "Numerous studies have shown that E2F3 functions in the control of tumour progression and is increased in different kinds of cancers." (PMID 32697386, 2020). "PUM1 and 2 were shown to impair E2F3 mRNA translation and promote miRNA-directed silencing of E2F3 expression in cancer cells, suggesting a rather tumor-suppressive role of both RBPs." (PMID 32761127, 2020). "E2F3 is critical for the transcriptional activation of various oncogenes controlling the rate of proliferation of both tumor and primary cells." (PMID 32117628, 2020). "Our qRT-PCR assays revealed an upregulation of E2F3 in ESCC tumor specimens compared with adjacent normal tissues." (PMID 33680929, 2020). "Taken together, these data suggested that RBAT1 sustains tumor cell oncogenicity by activating E2F3 signaling." (PMID 32669100, 2020).
tumor (continued). "One example is our observation that E2F pathway signatures were elevated in the MMTV-PyMT model, and we ultimately validated the role for E2F1, E2F3, and E2F3 in tumor progression using mouse models." (PMID 31341204, 2019). "Our analysis suggested that let7c-5p-NRAS and miR-125b-5p-E2F2/E2F3 are several tumor suppressive pathways in HBV-related HCC." (PMID 30602391, 2019). "In summary, our results indicated that the mRNA expression levels of E2F1, E2F3, E2F5, and E2F8 were significantly upregulated, and obvious and negatively associated with tumor stage for OC." (PMID 30967995, 2019). "In our study, it was shown that the expression level of E2F3 was markedly increased in metastatic GC samples and GC cell lines, indicating the tumour activator role of E2F3." (PMID 31423109, 2019). "Recent studies have shown that E2F3 can promote the growth of tumor cells by accelerating the metabolism of glucose." (PMID 31582908, 2019). "We also found that E2F3 expression was significantly and negatively correlated with tumor stage in patients with OC." (PMID 30967995, 2019). "In this study, miR-34a expression inhibited tumor cell proliferation and colony formation by downregulating E2F transcription factor 3 (E2F3) and survivin." (PMID 30563114, 2018). "Consistently, both HOXB9 and E2F3 protein levels were decreased in the tumor with lentiviruses carrying HOXB9 shRNA, compared with control shRNA." (PMID 29724991, 2018). "RB1, which is regulated by CDK4, showed a significantly lower expression in CDKN2Ahigh (p < 0.001) and the downstream transcription factor gene E2F3 was significantly higher expressed in CDKN2Ahigh tumours (p < 0.001)." (PMID 30258198, 2018). "XIST induced the upregulation of E2F3 (E2F transcription factor 3), which is a critical protein for tumor cell proliferation." (PMID 29147648, 2017). "Survivin, which belongs to the inhibitor of apoptosis proteins (IAP) family, plays a critical role in tumor progression and chemo- or radioresistance and its promoter activity was reported to be regulated by E2F3." (PMID 28947999, 2017). "The forces driving Sc/NE‐like and GU tumours into one consensus cluster are most likely a high proliferation rate and frequent E2F3, CDKAL1 and SOX4 genomic amplification at 6p22, which are characteristic of both subtypes." (PMID 28195647, 2017). "Meanwhile, it was also found that overexpression of miR-34a significantly inhibited tumor migration in HNSCC cell lines via downregulation of E2F3 and surviving." (PMID 28947999, 2017). "Selected miRNAs have a role in tumor progression, as e.g., miR-503 directly targets L1 adhesion molecule (L1CAM) and E2F transcription factor 3 (E2F3) mRNAs involved in tumor progression." (PMID 28289479, 2017). "Consistent with the mRNA level data, depletion of E2F3 severely impaired HIF-2α expression in tumor cells 786-O and OS-RC-2 transfected with siE2F3." (PMID 28903320, 2017). "In prostate cancer (PCa), miR-125b was fond to be regulated by 1,25-dihydroxyvitamin D and function as a tumor suppressor via regulation of E2F3." (PMID 28947999, 2017). "Recent studies have discovered several pathways that directly regulate multifunctional E2F3, presenting a significant tumor supervisor gene and a promising therapeutic target for the treatment of human cancers." (PMID 28947999, 2017). "In HCC, PPIX was testified to inhibit mesenchymal tumor angiogenesis, depending on the increase of miR-199a-5p by targeting E2F3." (PMID 28947999, 2017). "In some situation, it is important for E2F3 to regulate cellular proliferation of both primary and tumor cells via induction of apoptosis by DNA damage." (PMID 28947999, 2017). "Another study showed that miR-152 functions as a tumor suppressor in EC, and E2F3, MET, and Rictor were identified as novel candidate targets of miR-152." (PMID 28947999, 2017).